HOXC9 (homeobox C9)
Diseases named in the same sentence as HOXC9 in open-access papers (continued):
Sharing a sentence is not in itself a finding about the gene and the disease.
gastric tumor (1 paper, 2025). "Although this study does not describe the specific effect of HOXC9 on the phosphorylation of STAT1, targeted inhibition of HOXC9 in gastric tumor cells may enhance the IFN-γ/STAT1 signaling, thereby overcoming tumor-induced resistance to IFN-γ-mediated apoptosis." (PMID 40909948, 2025).
Hashimoto thyroiditis (1 paper, 2023). An autoimmune disorder caused by the production of autoantibodies against thyroid tissue. "Studies have linked low expression of HOXC9 to various conditions, including lymph node metastasis, papillary thyroid cancer, and Hashimoto’s thyroiditis." (PMID 37915086, 2023).
Hypertension (1 paper, 2023). The presence of chronic increased pressure in the systemic arterial system. "Multiple HOXC genes: HOXC-AS1-3, HOXC4, HOXC5, HOCX6, HOXC8, HOXC9 and HOXC10 were also shared between subsets of GORD, hypertension and precordial pain." (PMID 37410157, 2023).
Infertility (1 paper, 2019). "The strongly synergistic phenotype, with Hoxc9,10,11 female mice showing normal fertility, and AD+/− females showing approximate 50% reduced fertility, while ACD+/− mice show complete infertility, certainly argues in favor of redundancy." (PMID 30872674, 2019). "In this study we identify novel female fertility function for the Hoxc9,10,11 genes, with ACD+/− mice showing a much more severe infertility phenotype than AD+/− mice." (PMID 30872674, 2019).
keloid (1 paper, 2023). An irregularly shaped, elevated mark on the skin caused by deposits of excessive amounts of collagen during wound healing. "Our findings demonstrate that HOXC9 is critical in keloid formation and intricately linked to the keloid immune microenvironment." (PMID 37915086, 2023). "Furthermore, we identified key gene sets associated with the upregulation of HOXC9, further highlighting its connection to keloid formation and the immune microenvironment." (PMID 37915086, 2023). "It was found that HOXC9 was closely associated with the immune microenvironment of keloids." (PMID 37915086, 2023). "Consequently, HOXC9 may play a crucial role in cell proliferation, cell migration, angiogenesis, and other activities significantly linked to keloid formation." (PMID 37915086, 2023). "HOXC9 has been shown to exhibit a certain relationship with T-cell activity, which is a factor that has previously been discussed in the context of keloids." (PMID 37915086, 2023). "In this study, we performed bioinformatics analyses to detect key genes, such as HOXC9, which exhibited differential expression between normal and keloid tissues." (PMID 37915086, 2023). "Using this comprehensive approach, we discovered a key gene, HOXC9, that was related to keloids in the GSE7890 and GSE83286 data sets." (PMID 37915086, 2023). "Validating the role and expression of HOXC9 in keloids through various methods can pave the way for its clinical use." (PMID 37915086, 2023). "In our study, we not only compared the differences in HOXC9 expression between normal and keloid tissues but also highlighted the aberrant HOXC9 expression in keloids by evaluating its expression in normal tissues." (PMID 37915086, 2023). "This shows that HOXC9 can serve as a potential biomarker and therapeutic target for keloids." (PMID 37915086, 2023). "Our study findings suggest that HOXC9 may influence the immune microenvironment of keloids, thereby promoting their growth." (PMID 37915086, 2023). "However, HOXC9's specific expression pattern in keloid tissues indicated its crucial role in keloid formation regulation." (PMID 37915086, 2023). "Collectively, our findings underscore the critical function of HOXC9 in keloids." (PMID 37915086, 2023). "Thus, we investigated immune cell infiltration in the keloid and normal groups, as well as the correlation between HOXC9 and these immune cells." (PMID 37915086, 2023). "HOXC9 has been linked to different disorders, despite not previously being connected to keloids." (PMID 37915086, 2023). "Given the findings of differential and enrichment analyses, we hypothesize that HOXC9 may promote keloid formation by promoting cell proliferation and migration, increasing extracellular matrix deposition, and enhancing angiogenesis in keloid tissues." (PMID 37915086, 2023). "HOXC9 may have an impact on angiogenesis, which is crucial for the formation of keloids." (PMID 37915086, 2023). "Cross-validation analysis in the LASSO regression model selected the optimal λ value, minimizing error and finding three keloid-related genes: HSPA2, HECW2, and homeobox C9 (HOXC9)." (PMID 37915086, 2023).
lung adenocarcinoma (1 paper, 2024). A carcinoma that arises from the lung and is characterized by the presence of malignant glandular epithelial cells. "This study explores the predictive significance of HOXC9 for ICI plus chemotherapy efficacy in lung adenocarcinoma (LUAD)." (PMID 38446596, 2024).
myeloma (1 paper, 2021). "Some of these TFs were specifically downregulated in MSCs of active myeloma (RUNX2 and TEAD2), others were already downregulated in precursor myeloma stages (HOXC9 and CEBPD), whereas other TFs, including HOXA2 and ATF3, did not change their expression in any myeloma stages." (PMID 33462210, 2021).
Oral leukoplakia (1 paper, 2025). A thickened white patch on the oral mucosa that cannot be rubbed off. "However, it is currently unclear whether HOXC9 can promote the malignant transformation of oral leukoplakia by increasing the cell stemness of oral leukoplakia." (PMID 39895798, 2025). "The increased expression of HOXC9 in oral epithelium tissue with increasing malignancy and its promotion of CSCs and EMT indicate a close relationship with the malignant transformation of oral leukoplakia." (PMID 39895798, 2025). "In conclusion, we showed that HOXC9 knockdown can restore the CSCs and migration abilities of DOK cells overexpressing HOXC-AS1, thereby suggesting that HOXC-AS1 interacts with HOXC9 to increase tumor stemness of oral leukoplakia and promote malignant transformation of oral leukoplakia." (PMID 39895798, 2025).
renal agenesis (1 paper, 2018). Renal agenesis (RA) is a form of renal tract malformation characterized by the complete absence of development of one or both kidneys (unilateral RA or bilateral RA respectively), accompanied by absent ureter(s). "Conversely, renal agenesis was rarely observed in Hoxc9,10,11−/− Hoxd9,10,11−/− mutants (1 out of a total of 25 mutants examined), and nephrogenesis continued through E18.5 (Q’)." (PMID 29679048, 2018). "However, in mice with a single wild type copy of Hoxa11 present (Hoxa9,10−/−11+/− Hoxc9,10,11−/−), renal agenesis occurred in only 16% of mutants." (PMID 29679048, 2018).
renal cell carcinoma (1 paper, 2025). "In addition, the PRAT browning process has been specifically detected in renal cell carcinoma (RCC), being characterized by upregulated expression of brown/beige adipocytes markers (UCP1, PPAR-ɣ, c/EBPα, and PGC1α) and downregulated white fat cells markers, such as LEPTIN, SHOX2, HOXC8, and HOXC9." (PMID 40227577, 2025).
tumor (21 papers, 2009 to 2025). "In line with tumor growth patterns, the downregulation of Hoxc9 was associated with a significant increase in activated CD8+ T cells and IFN-γ production." (PMID 38446596, 2024). "At the facet of genomic exploration, through the online database cBioPortal, HOXC9 genetic mutations and alterations landscape were investigated in various tumor samples from TCGA datasets." (PMID 38446596, 2024). "HOXC9, a member of the HOX family, is highly expressed in various tumors such as colorectal cancer, gastric cancer 4 and is related to tumor malignancy and an increased risk of distant metastasis, and is thus an indicator of poor prognosis." (PMID 39895798, 2025). "In vitro experiments further demonstrated that regulation of Hoxc9 expression significantly impacted the proliferation, migration and invasion of two murine tumor cell lines, CMT167 and LLC." (PMID 38446596, 2024). "KDM6B expression is induced by retinoic acid via HOXC9 and inhibits tumor cell growth by promoting cell differentiation." (PMID 39239542, 2024). "HOXC9, known for its role in oncogenesis and creating a suppressive tumor microenvironment (TME), shows promise in enhancing predictive precision when included as a TME biomarker." (PMID 38446596, 2024). "Subsequently, tumor-bearing murine models were established to validate the inverse relationship between Hoxc9 expression and effective CD8+ T cells." (PMID 38446596, 2024). "As anticipated, the most substantial disparity in tumor sizes was observed between the control group treated with IgG and the Hoxc9 knockdown group subjected to PD-1 blockade (P<0.001)." (PMID 38446596, 2024). "In NSCLC, hsa-miR-495 binds to the HOXC93-UTR region and inhibits its expression, suggesting that it plays a tumor suppressor role in the MIR-495/HOXC9 pathway." (PMID 36635678, 2023). "Taken together, our study found that hsa_circ_0020123 functioned like a tumor promoter via a novel hsa_circ_0020123/miR-495/HOXC9 axis, highlighting its possibility as a new NSCLC therapeutic target." (PMID 32927434, 2020). "Comparing benign to tumour samples, HOXA6 (p = 4.26 × 10−5), HOXB6 (p = 0.001), HOXC5 (p = 4.69 × 10−5), HOXC6 (p = 3.02 × 10−28), and HOXC9 (p = 0.0001) all showed significantly greater expression in tumour samples, with HOXC6 having by far the greater fold difference." (PMID 40725480, 2025). "Besides, a study on gastric cancers has revealed that HOXC9 contributes to tumor progression by inhibiting STAT1 signaling." (PMID 40909948, 2025). "Then, the correlations between HOXC9 expression level and different clinical variables in LUAD were analyzed via UALCAN tools, which indicated higher HOXC9 expression was significantly associated with higher individual stages and tumor grade." (PMID 38446596, 2024). "Additionally, with the treatment of PD-1 blockade, concurrent with tumor growth dynamics, the downregulation of Hoxc9 exhibited a pronounced augmentation in CD3+ T cell infiltration, activation of CD8+ T cells, and an upsurge in IFN-γ production (P<0.001)." (PMID 38446596, 2024). "Recent studies have found that high expression of HOXC9 induces EMT in a variety of cancer cell lines 4, promotes the motility of tumor cells and enhances their self-renewal capabilities." (PMID 39895798, 2025). "We next performed rescue experiments, which revealed the partial reversal of the inhibitory effects of HOXC-AS1 on tumor sphere formation and EMT in HOXC9 OE DOK cells." (PMID 39895798, 2025). "To confirm this finding, we compared HOXC9 protein level between adjacent normal and cancerous tissues from clinical LUAD samples, and also found it was upregulated in tumor sample." (PMID 38446596, 2024). "Using RNA-seq data from 498 NB tumor samples, we observed that low expression of HOXC8 and HOXC9 correlates with poor survival, and this is consistent with an earlier report." (PMID 39528654, 2024).
tumor (continued). "Various studies reported that miR-26a acts as a tumor suppressor by downregulating c-MYC pathway, cAMP regulated phosphoprotein 19 (ARPP19), HOXC9." (PMID 32512882, 2020). "miR-495 bound to the HOXC9 3'-UTR region to suppress its expression, suggesting a role as a tumor suppressor in the miR-495/HOXC9 pathway in NSCLC." (PMID 32927434, 2020). "As for tumor volume, with or without ICIs treatment, knockdown of Hoxc9 significantly inhibited the growth of tumors." (PMID 38446596, 2024). "Furthermore, 30 clinical CRC tissues (including tumor tissues and the corresponding adjacent tumor tissues as well as normal tissues) were collected, and the expression of FABP4, HOXC9, INHBB, NKAIN4, and PLXNB3 was determined using RT-PCR." (PMID 35721480, 2022). "Results of IHC analyses of DDX39A, HMGA1, HMGA2, HOXC9, and PBX1 expression in tumor samples." (PMID 31188873, 2019). "Furthermore, ESCC from patients with tobacco smoking habits and with poorly tumor grades showed HOXC9 overexpression relative to never-smokers and patients with other tumor grades, respectively." (PMID 39596630, 2024). "Low expression of FABP4 in tumor tissues (p < 0.05) was validated in five datasets, the lower expression of PLXNB3, INHBB and NKAIN4 in tumor tissues was verified in three datasets (p < 0.05), and the decreased expression of HOXC9 and was validated in one dataset, respectively (p < 0.05)." (PMID 35721480, 2022).
cancer (9 papers, 2008 to 2025). A tumor composed of atypical neoplastic, often pleomorphic cells that invade other tissues. "The main type of genetic alterations in HOXC9 was “mutation”, which were observed in bulk of TCGA cancers, and the “amplification” was the second most common." (PMID 38446596, 2024). "Functional experiments suggested that HOXC9 induces the acquisition of cancer stem cells (CSCs) and epithelial-to-mesenchymal transition (EMT)." (PMID 39895798, 2025). "Taken together, this suggests that HOXC9 knockdown suppressed cancer migration, invasion, and sphere-forming ability in HSC3." (PMID 39895798, 2025). "MicroRNA-193a-3p was proven to suppress cancer development by silencing multiple genes, including HOXC9." (PMID 31013831, 2019). "Activation of HOXC9 and HOXC11 in various cancers has been associated with cell proliferation and invasion." (PMID 28402266, 2017). "To investigate the potential role of the HOXC9 on OLK malignant transformation, we transduced Dysplastic Oral Keratinocyt (DOK) cell which is pre-cancer cell with a HOXC9-overexpressing vector and determined the self-renewal ability reflecting the cancer stem(-like) cells (CSCs) signature." (PMID 39895798, 2025). "Firstly, we assessed HOXC9 expression in pan-cancer data from TCGA and GTEx." (PMID 38446596, 2024). "Hence, promoting cell autophagy by directly silencing HOXC9 protein expression is a promising new cancer therapeutic strategy." (PMID 31013831, 2019). "On the contrary, there are also some genes, such as HOXB3, HOXD1, HOXC9, and HOXA13, that are highly expressed in some cancers and have better OS (p<0.05)." (PMID 39980564, 2025). "This is the first report of methylation in any cancer for five loci (CPVL, HOXC9, PAX8, PTPRN2, and SLC38A4), flagging these loci as potential novel cancer markers." (PMID 18616821, 2008). "Likewise, the buccal mucosa-derived H157 (RRID: CVCL_2468) cancer cell lines showed overexpression of HOXA10, HOXC6, HOXC9, HOXC10 and HOXD11 which was consistent with the cancer of the buccal mucosa." (PMID 35710803, 2022). "The results showed that some HOX genes in pan-cancer had significant strong correlation (R≥0.8): HOXA9 with HOXA10, HOXB5 with HOXB6 and HOXB8, HOXB8 with HOXB6 and HOXB9, HOXB3 with HOXB4 and HOXB5 and HOXB6, HOXC8 with HOXC9, HOXC9 with HOXC10, HOXD10 with HOXD11." (PMID 39980564, 2025).
HOXC9 also shares sentences with these, for which no sentence is quoted: Insulin resistance (2 papers); non-small cell lung carcinoma (2); astrocytoma (1); colorectal cancer (1); glioblastoma (1); head and neck squamous cell carcinoma (1); kidney cancer (1); leukemia (1); lung squamous cell carcinoma (1); lymph node metastasis (1); melanoma (1); mouth neoplasms (1); nasopharyngeal carcinoma (1); oral squamous cell carcinoma (1); papillary thyroid cancer (1).